MAP3K13 (mitogen-activated protein kinase kinase kinase 13)
Description:
Activates the JUN N-terminal pathway through activation of the MAP kinase kinase MAP2K7. Acts synergistically with PRDX3 to regulate the activation of NF-kappa-B in the cytosol. This activation is kinase-dependent and involves activating the IKK complex, the IKBKB-containing complex that phosphorylates inhibitors of NF-kappa-B.
Synonyms: MLK; LZK; MEKK13
Tractability: Small molecule: a drug acting on it is in phase 2 or 3 trials; a high-quality ligand is known; it belongs to a druggable protein family. Antibody: UniProt places it where antibodies can reach, with high confidence. PROTAC: a small molecule that binds it is known.
Target class: TKL protein kinase group; Kinase; TKL protein kinase LZK subfamily; Protein Kinase; Enzyme; TKL protein kinase MLK family
Gene: Protein-coding gene on chromosome 3 (185,282,941 to 185,489,094, forward strand). Ensembl gene ENSG00000073803.
Subcellular location: Cytoplasm; Membrane
Subcellular location (Human Protein Atlas): Centriolar satellite; Cytosol; Nucleoplasm
Gene Ontology:
Molecular function: enzyme binding; identical protein binding; IkappaB kinase complex binding; MAP kinase kinase kinase activity; protein binding; protein homodimerization activity; protein serine/threonine kinase activity; protein kinase binding; protein serine/threonine kinase activator activity; ATP binding; protein kinase activity; protein serine kinase activity
Biological process: JNK cascade; positive regulation of canonical NF-kappaB signal transduction; stress-activated MAPK cascade; positive regulation of axon extension; positive regulation of branching morphogenesis of a nerve; positive regulation of neuron maturation; positive regulation of neuron projection arborization; intracellular signal transduction
Cellular component: membrane; cytoplasm
Genetic constraint (gnomAD): Loss-of-function variants: 43 observed, 85.03 expected, observed/expected ratio (o/e) 0.51, 90% interval 0.4 to 0.65. The upper end of that interval is the gene's LOEUF score, 0.65, which puts it in group 2 of 6, group 1 being the genes least tolerant of losing a copy. Missense variants: 841 observed, 1,178.1 expected, observed/expected ratio (o/e) 0.71, 90% interval 0.67 to 0.76. Synonymous variants: 369 observed, 436 expected, observed/expected ratio (o/e) 0.85, 90% interval 0.78 to 0.92.
Cancer hallmarks: proliferative signalling (promotes)
Homologues: Orthologues: chimpanzee MAP3K13 (99% identical), macaque MAP3K13 (99% identical), pig MAP3K13 (94% identical), dog MAP3K13 (93% identical), rabbit MAP3K13 (92% identical), guinea pig MAP3K13 (90% identical), mouse Map3k13 (89% identical), rat Map3k13 (88% identical), tropical clawed frog map3k13 (73% identical), zebrafish MAP3K13 (66% identical). Paralogues in human: MAP3K12 (50% identical), MAP3K9 (26% identical), MAP3K21 (25% identical), MAP3K10 (24% identical), MAP3K11 (21% identical), MAP3K20 (13% identical), TNNI3K (13% identical), BRAF (11% identical), LRRK2 (11% identical), TESK2 (11% identical), KSR2 (11% identical), RIPK1 (11% identical), and 11 more.
Diseases named in the same sentence as MAP3K13 in open-access papers:
MAP3K13 is named in the same sentence as 39 diseases in open-access papers, as found by Europe PMC text mining. Sharing a sentence is not in itself a finding about the gene and the disease. The quoted sentences say what the papers report.
breast carcinoma (9 papers, 2013 to 2025). "In breast cancer, high MAP3K13 expression is associated with poor patient survival." (PMID 34229645, 2021). "Driver mutations of MAP3K13 have been identified previously in breast cancer, whereas inactivating mutations may abrogate signaling pathways that increase JUN kinase function in breast cancer." (PMID 26918941, 2016). "A similar type of regulatory pattern has been reported in breast cancer in which microRNA-206 impacted cancer cell proliferation by inducing restraint of MAP3K13." (PMID 35311629, 2022). "Enforced MAP3K13 expression in breast cancer cells stabilizes MYC oncogene and promotes its transcriptional activity." (PMID 34229645, 2021). "All these data strongly support the idea that miR-206 and MAP3K13 inhibits and promotes development of breast cancer by ultimately controlling Myc protein level, respectively." (PMID 26918941, 2016). "In summary, our study has demonstrated a significant role for miR-206 and MAP3K13 in regulating the viability of breast cancer cells with high levels of Myc expression." (PMID 26918941, 2016). "Gene expression analyses of breast cancers expressing high levels of Myc indicated that low miR-206 expression and high MAP3K13 expression correlated with poor patient survival." (PMID 26918941, 2016). "If so, these data would predict that Myc-high human breast cancers with correspondingly high MAP3K13 or low miR-206 expression may correlate with poor survival." (PMID 26918941, 2016). "We thus determined independently whether Myc levels correlated inversely with survival in breast cancer and also examined the relationship of Myc levels to those for MAP3K13." (PMID 26918941, 2016). "Future studies should focus on the phenotypes of MAP3K13 transgenic and knockout mice and whether miR-206 suppresses Myc-mediated tumorigenesis only in breast cancer or is a more general regulator." (PMID 26918941, 2016).
head and neck squamous cell carcinoma (3 papers, 2021 to 2025). A squamous cell carcinoma that arises from any of the following anatomic sites: lip and oral cavity, nasal cavity, paranasal sinuses, pharynx, larynx, and salivary glands. "MAP3K13 (encoding LZK)-amplified head and neck squamous cell carcinoma cells harboring 3q gain depend on LZK expression for cell viability and colony formation." (PMID 39847581, 2025). "MAP3K13 is proved to be an amplified driver gene in head and neck squamous cell carcinoma (HNSCC)." (PMID 34229645, 2021). "Although recent studies on MAP3K13, the human homolog of Wnd, have revealed its tumor promoting roles in head and neck squamous cell carcinoma (HNSCC) and hepatocellular carcinoma (HCC) patients, the mechanism by which Wnd/MAP3K13 regulates tissue growth remains underexplored." (PMID 33937258, 2021).
breast tumors (2 papers, 2013 to 2016). "Our findings also implicate MAP3K13 as being essential for tumor growth by these cells and that its levels correlate with poor patient survival in Myc-high human breast tumors." (PMID 26918941, 2016).
colon cancer (2 papers, 2021 to 2024). "Our results suggested that LINC01287 had a positively association with MAP3K13 level in colon cancer patients." (PMID 34229645, 2021). "Taken together, our results indicated that restored MAP3K13 expression or miR-4500 knockdown partially reversed the effects caused by LINC01287 depletion in colon cancer cells." (PMID 34229645, 2021). "Restored MAP3K13 expression or miR-4500 knockdown partially abrogated the effects of silencing LINC01287 in colon cancer cells." (PMID 34229645, 2021). "Our findings demonstrated that the LINC01287/miR-4500/MAP3K13 axis promoted progression of colon cancer." (PMID 34229645, 2021). "Moreover, restoring MAP3K13 expression abolished the effects caused by LINC01287 knockdown, indicating the oncogenic functions of MAP3K13 in colon cancer cells." (PMID 34229645, 2021). "Notably, the expression of MAP3K13 was conversely correlated with miR-4500 expression in colon cancer patients." (PMID 34229645, 2021). "In our study, we demonstrated that LINC01287 overexpression facilitated proliferation, migration, invasion and EMT of colon cancer cells, and this might due to sponging miR-4500 and mediating MAP3K13 expression." (PMID 34229645, 2021). "Knockdown of LINC01287 inhibits colon cancer cell migration and invasion through the LINC01287/miR-4500/MAP3K13 axis." (PMID 39026978, 2024).
ovarian carcinoma (2 papers, 2019 to 2022). A malignant neoplasm originating from the surface ovarian epithelium. "Several protein kinases within this amplicon have been characterized as genetic drivers in different malignancies, including PKCι (PRKCI) in NSCLC and ovarian cancer, or LZK (MAP3K13) in HNSCC." (PMID 31817861, 2019).
polycystic ovary syndrome (2 papers, 2022 to 2025). A disorder that manifests as multiple cysts on the ovaries. "In polycystic ovary syndrome, lnc-MAP3K13-7:1 inhibited the proliferation of ovarian GCs via DNMT1 downregulation mediated by CDKN1A promoter hypomethylation." (PMID 40214477, 2025).
epilepsy (1 paper, 2025). A brain disorder characterized by episodes of abnormally increased neuronal discharge resulting in transient episodes of sensory or motor neurological dysfunction, or psychic dysfunction. "Sgk3, Gsk3a, and Stk38, as well as other stress kinases that we found to be overexpressed in the brainstem, such as Map3k13, have been less well-studied in the context of epilepsy." (PMID 41511350, 2025).
head and neck cancer (1 paper, 2021). A primary or metastatic malignant neoplasm affecting the head and neck.
liver cancer (1 paper, 2022). An epithelial or non-epithelial malignant neoplasm that arises from the liver. "The results from GSEA indicated that the low expression level of MAP3K13 was involved in the dynamics underlying liver cancer including the myc pathway, JNK pathway, and metastasis, resulting in the decrease in liver cancer survival rates." (PMID 35311629, 2022).
metabolic syndrome (1 paper, 2018). A cluster of metabolic risk factors for CARDIOVASCULAR DISEASES and TYPE 2 DIABETES MELLITUS. "The top differentially methylated CpG island associated with metabolic syndrome in females was in the gene encoding for the mitogen-activated protein kinase kinase kinase 13 (MAP3K13) protein." (PMID 29850476, 2018). "Three sites within the MAP3K13 gene at genomic locations Chr3:185000779, Chr3:185000774, and Chr3:185000760 were associated with metabolic syndrome status in females after adjusting for age, race, smoking status, and antipsychotic type (p = 0.01, 0.04, and 0.01, resp)." (PMID 29850476, 2018). "Consistent with the discovery analysis, hypomethylation of MAP3K13 was seen in female subjects with metabolic syndrome." (PMID 29850476, 2018). "Overall, female subjects with metabolic syndrome had lower methylation in the investigated MAP3K13 CpG island (both in the discovery and validation analyses) compared to female subjects without metabolic syndrome which may suggest higher expression and possibly activity of the kinase." (PMID 29850476, 2018).
tumor (17 papers, 2013 to 2025). "In summary, our study provides evidence that circMAP3K13 encodes a functional protein, MAP3K13-232aa, which activates NF-κB signaling, promotes pyroptosis, and suppresses tumor progression in GC." (PMID 40890114, 2025). "In vitro and in vivo assays further demonstrated that MAP3K13-232aa inhibited GC cell proliferation and migration, reinforcing the tumor-suppressive function of pyroptosis mediated by circMAP3K13." (PMID 40890114, 2025). "Together, these results suggest that MAP3K13-232aa has a tumor-suppressive role in GC, inhibiting cell proliferation, migration, and invasion." (PMID 40890114, 2025). "H&E staining revealed that mice injected with MAP3K13-232aa–overexpressing cells had fewer metastatic tumor nodules in the lungs compared to the control group." (PMID 40890114, 2025). "Mice injected with MAP3K13-232aa–overexpressing cells developed tumors but with markedly reduced tumor volumes and weights compared to controls." (PMID 40890114, 2025). "Tumor fragments from HNSCC patients containing amplified or diploid MAP3K13 were obtained from the NIH PDMR." (PMID 39605563, 2024). "Inhibition of LZK catalytic activity suppressed tumor growth in HNSCC PDX models with amplified MAP3K13." (PMID 39605563, 2024). "The levels of AFP, the stage of BCLC, status of Cirrhosis, tumor size, levels of MAP3K13, and levels of MAP3K15 were incorporated into a nomogram for a visual representation of OS." (PMID 35311629, 2022). "Our study showed that MAP3K13 is a tumor suppressor and the genetic regulation of MAP3K significantly affects the JNK signaling pathway and apoptotic phenotype of HCC cells." (PMID 35311629, 2022). "By inhibiting MAP3K13, miR-206 inhibits the stability of Myc protein and thus of tumor cell survival and proliferation." (PMID 26918941, 2016). "Moreover, MAP3K13 is demonstrate as a positive regulator of Myc oncogene, and promotes tumor development by stabilizing Myc through RIM25-FBXW7α signaling axis." (PMID 34229645, 2021). "MAP3K13 upregulation has been reported to correlate with a poor outcome in tumor progression." (PMID 34503107, 2021). "Few other genes such as MAP3K13 and JAK2 was found to be mutated only in certain tumor pieces." (PMID 29187174, 2017). "To validate the tumor-suppressive role of MAP3K13-232aa in vivo, we established stably transfected MKN-45 cell lines overexpressing circMAP3K13, linear MAP3K13-232aa, or an empty vector." (PMID 40890114, 2025). "In addition, four genes (BAIAO3, MECOM, MAP3K13, and NOS) were found to have decreased expression in tumor from patients who experienced recurrence compared to those who did not." (PMID 34729947, 2021). "GNE-3511 reduced tumor growth for both MAP3K13-amplified PDX models and had little effect on the 2 PDX models without increased MAP3K13 expression." (PMID 39605563, 2024). "Although not as effective as BCLC, we did find that MAP3K13 and MAP3K15 were better than AFP and tumor size in predicting prognosis." (PMID 35311629, 2022).
cancer (14 papers, 2013 to 2025). A tumor composed of atypical neoplastic, often pleomorphic cells that invade other tissues. "Multiple cancer-associated genes are significantly downregulated in the translatome upon shMSI1 inhibition, including MAP3K13, transcriptional enhancers of MYC and genes essential in early development, NPM1 and KMT2A, respectively." (PMID 36473869, 2022). "Our findings show that depleting MAP3K13 significantly decreased the amount of phosphorylation on Ser62 of Myc, resulting in increased protein instability and an associated loss of transcriptional activity in cancer cells with the highest levels of Myc." (PMID 26918941, 2016). "Results of GSEA revealed that low levels of expression of MAP3K13 and MAP3K15 were involved in dynamics underlying cancer development, and these were essentially consistent with the results of our own study." (PMID 35311629, 2022). "The critical link between miR-206 and MAP3K13 in the development of Myc over-expressing human cancers suggests potential points of therapeutic intervention for this molecular sub-category." (PMID 26918941, 2016). "Targeting MAP3K13 significantly decreased protein levels in all three cancer cells but significantly inhibited growth, soft agar colony formation and in vivo tumorigenesis only in the high Myc-expressing lines MB231 and HepG2." (PMID 26918941, 2016). "miR-206 inhibited MAP3K13, which resulted in Myc protein de-stabilization, and an inhibition of anchorage-independent growth and in vivo tumorigenesis by Myc over-expressing human cancer cells." (PMID 26918941, 2016). "Given that MAP3K13 appeared to be an important miR-206 target, we hypothesized that MAP3K13 would be important for Myc-driven human cancers." (PMID 26918941, 2016). "Our data indicate that miR-206 inhibits Myc-driven human cancer by directly targeting MAP3K13." (PMID 26918941, 2016). "Furthermore, previous reports suggest MAP3K13 exerts oncogenic roles in human cancers." (PMID 34229645, 2021). "Indeed, MAP3K13 exerts oncogenic activity in various cancers." (PMID 34229645, 2021). "More importantly 9 new cancer genes were identified; seven of them (ARID1B, CASP8, MAP3K1, MAP3K13, NCOR1, SMARCD1, CDKN1B) carried truncating mutations and were characterized by biallelic inactivation, suggesting that they were potentially recessive cancer susceptibility genes." (PMID 26561834, 2015). "MAP3K13 was found to be commonly expressed, but its expression was at a low level in cancer tissues, and HCC patients with a low level of expression of MAP3K13 typically have bad prognosis, which suggested that MAP3K13 was a tumor suppressor gene." (PMID 35311629, 2022). "For instance, MAP3K8, MAP3K13, NCF2, NF-κB (family), NFATC2, NF-κB (complex), and NR2F2 were significantly disturbed by myricetin treatment, which are belonging to cancer related MAPK/NF-κB inflammatory signaling pathway." (PMID 30956980, 2019). "MAP3K13, a gene in MAPK signaling pathway, is proved to be oncogenic in human cancers." (PMID 34229645, 2021). "To evaluate the necessity of MAP3K13 for anchorage-dependent and -independent proliferation in vitro and tumorigenesis in vivo, we examined the effect of targeting MAP3K13 in MB231, HepG2 and MCF-7 cancer cells using specific shRNA." (PMID 26918941, 2016). "As expected, ectopic expression of miR-206 decreased endogenous MAP3K13 at the mRNA and protein levels in high Myc-expressing MB231 and HepG2 cancer cells but not in low Myc-expressing MCF-7." (PMID 26918941, 2016).
MAP3K13 also shares sentences with these, for which no sentence is quoted: metastatic tumor (3 papers); cervical carcinoma (2); glioma (2); neurodegenerative disease (2); Obesity (2); Stroke (2); arterial occlusive disease (1); B-cell lymphoma (1); cerebral malaria (1); cognitive disorder (1); COVID-19 (1); gastric adenocarcinoma (1); hepatocellular carcinoma (1); hypertrophy (1); infection (1); ischemia (1); lung adenocarcinoma (1); lung carcinoma (1); melanoma (1); neuroblastoma (1); oral cancer (1); oropharyngeal squamous cell carcinoma (1); pancreatic cancer (1); Parkinson disease (1); renal cell carcinoma (1); spinal cord injury (1); squamous cell carcinoma (1).